RN7SL496P (RNA, 7SL, cytoplasmic 496, pseudogene)
Gene: Miscellaneous RNA gene on chromosome 7 (39,888,375 to 39,888,664, forward strand). Ensembl gene ENSG00000242855.
Homologues: Orthologues: chimpanzee Metazoa_SRP (99% identical), macaque Metazoa_SRP (91% identical). Paralogues in human: RN7SL2 (84% identical), RN7SL1 (83% identical), RN7SL3 (83% identical), RN7SL118P (82% identical), RN7SL679P (81% identical), RN7SL230P (81% identical), RN7SL769P (81% identical), RN7SL464P (81% identical), RN7SL559P (81% identical), RN7SL732P (81% identical), RN7SL45P (80% identical), RN7SL856P (80% identical), and 705 more.